CASP1 (caspase 1)
Diseases named in the same sentence as CASP1 in open-access papers (continued):
Sharing a sentence is not in itself a finding about the gene and the disease.
Sjogren syndrome (3 papers, 2015 to 2024). An autoimmune disorder in which immune cells attack and destroy the glands that produce tears and saliva. "In Sjogren’s syndrome, the concentration of caspase 1 in gingival crevicular fluid increased significantly, while the concentration of caspase 1 in peripheral plasma decreased, but the concentration of IL-1β in both parts increased significantly." (PMID 31367484, 2019).
Splenomegaly (3 papers, 2016 to 2024). Abnormal increased size of the spleen. "Inhibition of the NLRP3 inflammasome, or downstream caspase-1, prevented MAS-mediated upregulation of plasma IL-18 but interestingly did not alleviate key features of hyperinflammatory disease including hyperferritinaemia and splenomegaly." (PMID 38464243, 2024). "Inhibition of the NLRP3 inflammasome or the downstream caspase-1 prevented MAS-mediated upregulation of IL-18 in the plasma but, interestingly, did not alleviate key features of hyperinflammatory disease including hyperferritinaemia and splenomegaly." (PMID 38775430, 2024). "However, blockade of NLRP3, caspase-1 or IL-1 signalling was not sufficient to prevent the development of several features of hyperinflammatory disease, such as hyperferritinaemia and splenomegaly, suggesting that these traits occur independent of the NLRP3 inflammasome." (PMID 38775430, 2024).
sporotrichosis (3 papers, 2016 to 2025). The commonest and least serious of the deep mycoses, characterized by nodular lesions of the cutaneous and subcutaneous tissues. "NLRP3 and caspase-1 knockout mice were more susceptible to sporotrichosis." (PMID 34908455, 2021). "qPCR, western blot, and IHC/mIHC were employed to profile IL-18, IL-18 BP, caspase-1 and IL-18R axis, along with Th1,Th2, and Th17 cells and their specific cytokines in sporotrichosis lesions versus healthy skin." (PMID 40489556, 2025). "However, both the distribution and expression intensity of caspase-1 in the epidermis of sporotrichosis lesions were lower than those found in HCs." (PMID 40489556, 2025). "Indeed, the regulatory effects of the NLRP3/caspase-1 pyroptosis pathway against sporotrichosis upon Nd:YAG 1,064-nm laser treatment are worthy of further study." (PMID 34908455, 2021). "Additionally, gp60 may have interfered with caspase-1-dependent signaling pathways activation, which has proven to be important for the production of Th1 cytokines during experimental sporotrichosis." (PMID 27051673, 2016).
squamous cell carcinoma (3 papers, 2014 to 2020). A carcinoma arising from squamous epithelial cells. "Similarly, the expression of purinergic receptor P2X7, apoptosis-associated speck-like protein containing CARD, and pro-form caspase 1 in A253 cells derived from epidermoid carcinoma were highly upregulated in comparison to normal Human Salivary Gland cell line." (PMID 28430665, 2017). "Tgfbr1 and Pten were able to inhibit the expression of NLRP3, ASC, caspase-1, IL-1β, and IL-18 in a mouse squamous cell carcinoma of the head and neck model." (PMID 32723297, 2020). "We evaluated the influence of apoptosis-associated speck-like protein containing a caspase recruitment domain (ASC) and caspase (CASP)-1 in the antitumor immune response using a multistage model of squamous cell carcinoma (SCC) development." (PMID 25268644, 2014).
synovitis (3 papers, 2014 to 2023). Inflammation of a synovial membrane. "In our study, we explored the role of NLRP3 inflammasome in TMJOA synovitis and the therapeutic potential of caspase-1 and NLRP3 inhibitors." (PMID 36466156, 2022). "Studies in an air pouch model of synovitis also confirmed the activation of NLRP3/ASC/caspase 1 by hydroxyapatite crystals and supported a role in controlling neutrophil infiltration." (PMID 25175678, 2014).
synucleinopathies (3 papers, 2019 to 2022). "One possible explanation for the increased abundance of PTM aSyn variants such as CTT aSyn under conditions of synucleinopathy may be that certain enzymes like calpains and caspase-1 are processing aSyn in the accumulated inclusion bodies." (PMID 35659116, 2022). "We demonstrated that caspase inhibition reversed aSYN-induced mitochondrial dysfunction and neuronal death, suggesting that caspase inhibition and specifically inhibition of caspase-1 might be an effective therapeutic strategy in synucleinopathies including PD." (PMID 31727879, 2019).
Thrombocytopenia (3 papers, 2022). A reduction in the number of circulating thrombocytes. "In the current study, thrombocytopenia and active caspase-1 showed opposite trends, suggesting that there must be a link between them." (PMID 35945940, 2022). "In addition, challenges of NDs induced less platelet pyroptosis and displayed less thrombocytopenia in P-selectin (Selp-/-), Nlrp3 (Nlrp3-/-) and caspase-1 (Casp1-/-) mutants, as compared to the wild type mice." (PMID 35444640, 2022). "We found that NAC pretreatment could inhibit the expression of platelet NLRP3 and cleaved caspase-1 as well as platelet activation and thrombocytopenia in HS rats, indicating that ROS could activate NLRP3 inflammasome in platelets and may be invovled in thrombocytopenia." (PMID 35945940, 2022).
thyroid cancer (3 papers, 2017 to 2023).
toxoplasmosis (3 papers, 2014 to 2023). A parasitic disease contracted by the ingestion or fetal transmission of toxoplasma gondii. "The contribution of interactions between human toxoplasmosis and the inflammatory process indicates that the expression of IL-1 in human monocytes depends on ASC and caspase-1, which is an adapter protein that binds caspase-1 to NLRP3/CARDB or NLRP1/caspase-5 in the flammomasome." (PMID 36839525, 2023).
tuberculosis (3 papers, 2010 to 2022). A chronic, recurrent infection caused by the bacterium Mycobacterium tuberculosis. "In particular, low miR-20b-5p expression and activated NLRP3/caspase-1/IL-1β pathway were observed in a TB mouse model stably infected with M. tuberculosis." (PMID 32987746, 2020). "Some studies using caspase-1-/- mice to explore the role of pyroptosis in traumatic injury or noncognate tuberculosis showed that pyroptosis-related proteins were less prominent in caspase-1-/- mice than those in the WT mice." (PMID 35639503, 2022).
acute cystitis (2 papers, 2016 to 2025). An acute infection of the bladder. "Furthermore, Casp1-/- mice, which have a functional IL-1β deficiency due to defective IL-1β processing and secretion, did not develop acute cystitis." (PMID 27732661, 2016).
alcohol abuse (2 papers, 2023 to 2024). The use of alcoholic beverages to excess, either on individual occasions ("binge drinking") or as a regular practice. "Likewise, liver injury inflicted by alcohol abuse also exaggerates EV release, carrying inflammatory signaling molecules (NFκB, TLR4, IL-1 receptors, caspase-1) into the circulation." (PMID 38014253, 2023).
allergic asthma (2 papers, 2015 to 2024). A asthma with a basis in a pathological type I hypersensitivity reaction. "Research into the role of caspase-1 in allergic asthma has produced contradictory results." (PMID 26091108, 2015).
amyloid (2 papers, 2022). "Conversely, it has been shown that an NLRP3 deficiency can suppress brain caspase-1 and IL-1β activation, which remarkably inhibits amyloidosis and neuropathology, and ultimately enhances cognitive function in the AD mice model." (PMID 35327507, 2022). "The overexpression of Klotho has been reported to suppress neuroinflammation by inhibiting the NLRP3/caspase-1 pathway in amyloidosis mouse models." (PMID 35327507, 2022).
Arrhythmia (2 papers, 2016 to 2023). Any cardiac rhythm other than the normal sinus rhythm. "Importantly, Nlrp3−/− and Casp1−/− diabetic mice had lower arrhythmia vulnerability and severity in response to Caff/Dobu challenge when compared with diabetic WT mice." (PMID 27882934, 2016).
aspergillosis (2 papers, 2010 to 2014). Aspergillosis is an infection, growth, or allergic response caused by the Aspergillus fungus. "In contrast, inflammasome assembly during aspergillosis has never been described, although previous studies showing secretion of IL-1β by THP-1 during infection by A. fumigatus suggest that an inflammasome and caspase-1 must be activated." (PMID 20368800, 2010).
Atrophy (2 papers, 2021 to 2026). Any weakening or degeneration, especially through lack of use. "Inflammasome activity and gene expression of caspase-1 in Paracoccidioides brasiliensis indicates that pyroptosis participates in the induction of thymic atrophy." (PMID 34113341, 2021).
bladder cancer (2 papers, 2022 to 2025). "The Univariate Cox regression analysis revealed that eight PRGs (PRKACA, GSDMB, CASP9, GSDMD, CASP6, CASP8, AIM2, and CASP1) were significantly correlated with the prognosis in bladder cancer." (PMID 36120583, 2022). "Increased expression of caspase 1 was observed in bladder cancer cells, as well as the prevalence of pyroptosis, which suggested the secretion of HMGA2 in the plasma of bladder cancer patients." (PMID 40204943, 2025).
bronchopulmonary dysplasia (2 papers, 2025). Bronchopulmonary dysplasia is a chronic respiratory disease that results from complications related to lung injury during the treatment of infant acute respiratory distress syndrome in low-birth-weight premature infants or from abnormal lung development in older infants. "VX-765 inhibited NLRP3/Caspase-1/GSDMD-mediated macrophage pyroptosis in the mice lung tissue of bronchopulmonary dysplasia (BPD)." (PMID 40486518, 2025). "Emerging research has highlighted the pivotal role of the inflammasome-caspase-1 axis in the pathogenesis of bronchopulmonary dysplasia (BPD)." (PMID 41231039, 2025).
Cachexia (2 papers, 2016 to 2023). Severe weight loss, wasting of muscle, loss of appetite, and general debility related to a chronic disease. "We also observed that Caspase 1 gene expression increased in terminal cachexia, whereas Nod2 gene expression was increased only on T7, returning to basal levels in T14, whereas Nod1 and Hif‐1α gene expression did not change during the development of cachexia." (PMID 37177862, 2023).
carotid atherosclerosis (2 papers, 2022 to 2024). A thickening and loss of elasticity of the walls of carotid arteries that occur with formation of atherosclerotic plaques. "Consistent with previous works, our result showed that high expressions of NLRP3 inflammasome components such as c-caspase-1 and c-IL-1β were observed in carotid atherosclerosis." (PMID 35464766, 2022). "GSDMD, CASP1, NLRC4, AIM2, and IL18 were the key pyroptosis related genes, which might provide a new sight in the prevention of fatal strokes in advanced carotid atherosclerosis." (PMID 38167983, 2024).
cataract (2 papers, 2021 to 2022). Partial or complete opacity of the crystalline lens of one or both eyes that decreases visual acuity and eventually results in blindness. "H2O2-induced oxidative stress could activate NF-κB signaling and increase NLRP3 expression significantly in human lens epithelial cells via caspase-1 activation and maturation of IL-1β, which contributes to pyroptosis and the development of cataracts." (PMID 34925047, 2021). "Several studies have demonstrated that pyroptosis might have a role in cataract formation and that the levels of pyroptosis markers, such as NLRP3, pro-caspase-1, active caspase-1, GSDMD-N, IL-1β, and IL-18, are significantly increased in the capsule tissues or cells of cataract patients." (PMID 34925047, 2021).
cerebellar degeneration (2 papers, 2022 to 2025). Degeneration of the cerebellum. "To explore the mechanism underlying the protective effect of MCC950 in METH-induced cerebellar degeneration, we conducted an immunoblotting analysis of NLRP3 pathway proteins including NLRP3, ASC, Caspase-1, Cleaved Caspase-1 (P20), IL-1β and mature IL-1β." (PMID 35431795, 2022). "To explore the mechanisms involved in the METH-induced cerebellar degeneration, we quantified NLRP3-ASC-Caspase 1-IL-1β pathway protein levels." (PMID 35431795, 2022). "Collectively, these findings suggest that mature IL-1β secretion mediated by NLRP3-ASC-Caspase 1 may be a critical step in METH-induced cerebellar degeneration and highlight the neuroprotective properties of inflammasome inhibition in cerebellar degeneration." (PMID 35431795, 2022).
cerebrovascular diseases (2 papers, 2023 to 2025). "Neurological diseases can be broadly categorized into cerebrovascular diseases, and neurodegenerative diseases, which are closely associated with the AIM2-caspase-1-GSDMD and NLRP3-caspase-1-GSDMD inflammasome signaling pathways." (PMID 39994107, 2025).
cholesteatoma (2 papers, 2015 to 2021). A pathologic process characterized by the proliferation of keratinizing squamous epithelium resulting in the accumulation of keratin and cells in the middle ear and/or mastoid. "Furthermore, the levels of NLRP3, ASC, and caspase-1 mRNA were significantly upregulated in middle ear tissue samples from patients with cholesteatoma or chronic otitis media." (PMID 34805037, 2021). "NOD1 and many proapoptotic caspase genes such as CASP1, CASP2, CASP8, and CASP9 were not altered in cholesteatoma." (PMID 25922834, 2015).
Chronic colitis (2 papers, 2019 to 2023). A chronic inflammatory disease of the large intestine (colon, cecum and rectum). "Our results revealed that the activities of MPO, NFκB DNA binding, and caspase-1, and the levels of active caspase-3 were significantly increased in the chronic colitis rat group compared with normal rats." (PMID 37513865, 2023). "In chronic colitis, increased activity of caspase-1 leads to the production of pro-inflammatory cytokines and the perpetuation of the inflammatory response." (PMID 37513865, 2023). "Furthermore, our investigation revealed a negative correlation between the levels of β-hydroxybutyrate in rats with chronic colitis and several inflammatory markers, including MPO activity, ROS production, NLRP3 levels, caspase-1 activity, NFκB DNA binding activity, and the NGSDMD." (PMID 37513865, 2023).
chronic granulomatous disease (2 papers, 2012 to 2014). Chronic granulomatous disease (CGD) is a rare primary immunodeficiency, mainly affecting phagocytes, which is characterized by an increased susceptibility to severe and recurrent bacterial and fungal infections, along with the development of granulomas. "But studies in Chronic Granulomatous Disease (CGD) patients with mutations in four subunits of NADP oxidase complex show that despite the absence of ROS production, they have increased levels of caspase-1 activity and pro-inflammatory cytokine generation." (PMID 22393394, 2012).
chronic lymphocytic leukemia (2 papers, 2017 to 2021). "CASP1 single-nucleotide polymorphisms were associated with changes in NF-κB signaling and development of other non-Hodgkin lymphomas, including diffuse-large B cell lymphomas and small lymphocytic lymphoma/chronic lymphocytic leukemia." (PMID 29018799, 2017). "Furthermore, genetic variation of CASP1 is associated with risk of chronic lymphocytic leukemia." (PMID 33999861, 2021).
colon adenocarcinoma (2 papers, 2017 to 2025). "Furthermore, axitinib 37 serves as a pyroptotic agents in colon adenocarcinoma through caspase-1/GSDMD activation and pancreatic adenocarcinoma through caspase-3/GSDMC activation." (PMID 39316325, 2025). "Furthermore, septacidin 76 is used as pyroptotic agent in colon adenocarcinoma through caspase-1/GSDMD activation." (PMID 39316325, 2025).
corneal disease (2 papers, 2023 to 2025). "Collectively, these findings demonstrate a physiological role for NLRP3 and caspase-1 in regulating infection in a clinically relevant murine model of blinding corneal disease." (PMID 37730693, 2023). "Caspase-1/11-/- and Caspase-1-/- mice had more severe corneal disease and significantly elevated GFP and CFU compared with C57BL/6 mice." (PMID 37730693, 2023). "Overall, these findings support a role for NLRP3 and caspase-1 in regulating bacterial killing and corneal disease severity with no apparent role for NLRC4 and no requirement for GSDMD, GSDME, or neutrophil elastase." (PMID 37730693, 2023). "Also, in P. aeruginosa infection, NLRP3 and caspase-1, but not NLRC4 were required for IL -1β production, bacterial killing and corneal disease severity." (PMID 37730693, 2023).
cryptosporidiosis (2 papers, 2024 to 2025). Intestinal infection with organisms of the genus Cryptosporidium. "Hence, elevated levels of caspase-1 are associated with increased resistance to cryptosporidiosis." (PMID 40005845, 2025). "In particular, intrinsic activation of caspase-1 in epithelial cells has been shown to positively influence interleukin-18 (IL-18) secretion, which is important for activating immune reactions during cryptosporidiosis." (PMID 40005845, 2025).
cystic kidneys (2 papers, 2022 to 2024). "Transcriptome analysis of cystic kidneys by RNAseq in this study suggests a potential mechanistic connection between the Caspase-1/inflammasome and cystic disease." (PMID 36523654, 2022). "In initial studies we found that the expression of multiple cellular sensors that act upstream of Caspase-1/inflammasome activation are elevated in cystic kidneys of both human ADPKD and PKD model mice, suggesting that the inflammasome priming process has occurred." (PMID 36523654, 2022). "In keeping with these observations, control-ASO treated cystic kidneys showed elevated levels of the TNF-α and cleaved caspase-1; both were significantly reduced in mice treated with Glis2-ASO." (PMID 38693102, 2024). "Evidence is presented here for the first time that the Caspase-1/inflammasome is primed in PKD kidneys of both humans and mice and is activated in the cystic kidneys of female RC/RC mice, a human-orthologous PKD model mouse strain." (PMID 36523654, 2022).
dermatomyositis (2 papers, 2019 to 2024). Dermatomyositis (DM) is a type of idiopathic inflammatory myopathy characterized by evocative skin lesions and symmetrical proximal muscle weakness. "Yin Xi’s research group reported that compared to healthy controls, patients with polymyositis (PM) and dermatomyositis (DM) showed elevated levels of NLRP3, IL-1β, and IL-18 mRNA in muscle fiber tissues, as well as increased expression of NLRP3 and caspase-1 p20 protein subunit." (PMID 39723212, 2024).
encephalomyelitis (2 papers, 2022 to 2023). Inflammation of the brain and the spinal cord. "Progression of encephalomyelitis in the spinal cord was accompanied by increased expression of NLRP3, whereas loss of NLRP3, Casp1, ASC, or IL-1β in mice led to resistance to encephalomyelitis." (PMID 36669831, 2023).
endometritis (2 papers, 2022 to 2025). An acute or chronic, usually bacterial infectious process affecting the endometrium. "According to immunohistochemistry, the expression of caspase-1 in endometritis tissues was increased by sixfold compared to the healthy group, and the expression of caspase-4 was found to increase by sevenfold compared to the healthy group." (PMID 36430491, 2022). "The results demonstrated NLRP3 inflammasome activation in endometritis, evidenced by elevated protein levels of NLRP3, ASC, pro-Caspase-1, and cleaved Caspase-1, concurrent with Ang upregulation." (PMID 40723465, 2025). "Qualitative and quantitative analysis of major pyroptosis-related proteins (caspase-1, caspase-4, ASC, GSDMD-N, and NLRP3) in endometrial tissues showed that pyroptosis occurred in endometrial tissues of cows with endometritis." (PMID 36430491, 2022). "Therefore, we measured caspase-1/4, ASC, NLRP3, and GSDMD-N levels to determine whether pyroptosis occurs in endometritis." (PMID 36430491, 2022).
eosinophilia (2 papers, 2022 to 2023). "Caspase-1-deficient mice showed no alterations in general lung inflammatory parameters, but a marked reduction in eosinophilia." (PMID 35844541, 2022).